GZMB (granzyme B)
Diseases named in the same sentence as GZMB in open-access papers (continued):
Sharing a sentence is not in itself a finding about the gene and the disease.
tumor (continued). "Although the mechanisms by which basophils contribute to tumor suppression are not fully understood, certain mediators (e.g., granzyme B and TNF-α) released by these cells have tumor-killing properties." (PMID 40873585, 2025). "The blockade of the CD6-CD318 interaction by itolizumab increases the cytotoxic capacity of CD8 T and NK cells over CD318+ tumor lines, reverses the NKG2A/NKG2D ratio, and increases granzyme B and IFNγ production." (PMID 40391211, 2025). "Histological analyses further supported immune remodeling: tumor sections from PD-1-0520-treated mice showed increased necrosis (HE staining) and dense infiltration of CD8+ T cells, alongside elevated GZMB and IFN-γ." (PMID 41373467, 2025). "These interactions collectively result in reduced secretion of granzyme B and IFN-γ by NK cells, impairing their cytolytic function against tumor cells." (PMID 40643499, 2025). "In AML patients, the overexpression of CD155 on tumor cells promotes the endocytosis and degradation of DNAM-1 on ILC2s, leading to impaired GZMB secretion and cancer immune evasion." (PMID 41267084, 2025). "Through processes like granzyme B and perforin release, they can directly destroy tumor cells, and their IFN-γ production is essential for fostering anti-tumor immunity and preventing metastasis." (PMID 40453095, 2025). "In mixed cocultures that incorporated GSCs with NK‐92 cells, B7 increased NK cell‐mediated tumor‐killing activity by inducing GSCs apoptosis via LDH, GzmB, and perforin release." (PMID 40492418, 2025). "This combination therapy notably suppressed the recruitment of MDSCs and increased the tumor infiltration of IFN-γ + CD8 + T cells and Granzyme B + CD8 + T cells." (PMID 39987091, 2025). "This therapy utilizes a triple-killing mechanism (perforin/granzyme B, death ligand pathway, and ADCC) to achieve highly effective anti-tumor effects." (PMID 40904456, 2025). "The combination of anti-PD-1 and STM2457 treatment also markedly increased the levels of IFN-γ + and Granzyme B + CD8 + T cells in NAFLD-HCC tumors and exhibited synergistic inhibition of tumor growth in syngeneic orthotopic NAFLD-HCC models." (PMID 39987091, 2025). "in vivo, CD8+ CTLs, particularly GZMB+CD8+ T cells, serve as the primary anti‐tumour immune effectors by secreting crucial molecules such as GZMB and IFN‐γ." (PMID 40356247, 2025). "We found that tumor tissues had fewer infiltrating immune cells than normal lung tissues did, and tumors from patients with early-stage SCLC presented more granzyme B+/CD8+ T cells than those from patients with late-stage SCLC did." (PMID 40925909, 2025). "Consistently, the R-MAHA treatment enhanced CD8+ T-cell activation more potently than other treatments, as evidenced by elevated levels of tumor-infiltrating interferon-γ (IFN-γ)+CD8+ T cells and serum granzyme B (GZMB)." (PMID 40593710, 2025). "Tumor immune cell profiling in Bmal1ΔDC mice confirmed a blunted cytotoxic CD8+ T-cell response, with fewer IFN-γ+ and Granzyme B+ CD8+ T cells after ICT." (PMID 41279119, 2025). "Tumor-infiltrating CD8+ T cells (TILs) from DIO mice exhibit higher PD-1 expression and secrete less IFN-γ and granzyme B per cell, as measured by intracellular flow cytometry." (PMID 41516046, 2025). "mIF staining revealed significant increases in functional T cells (CD4+ granzyme B+ and CD8+ granzyme B+ T cells) and structural changes in tumor vessels (CD31/aSMA staining) in the SBI-0206965-treated group." (PMID 39744218, 2025). "ELISA analysis of tumor tissues revealed that B7 significantly enhanced IFN‐γ, TNF‐α, GzmB, and perforin levels (P < 0.05 vs vehicle), whereas CD155 overexpression diminished this immunostimulatory functionality of B7 (all P < 0.05 vs corresponding vehicle)." (PMID 40492418, 2025). "CD8+ T cells can secrete granzyme B (GZMB) and interferon-gamma (IFN-γ), enhancing their cytotoxicity against tumor cells." (PMID 40346484, 2025).
tumor (continued). "HSV-1 OV-mOX40L activated CD4 and CD8 T cells, as evidenced by increased IFNγ and granzyme b production, and increased migration of immune cells into the TME, similar to our observations with the UN-KC-6141 tumor model." (PMID 40430543, 2025). "The combined use of DMF and anti-PD-L1 antibody significantly increased the number of tumor-infiltrating CD8+ T cells and the levels of granzyme B, thereby enhancing the efficacy of immunotherapy in mice." (PMID 40461489, 2025). "TILs elicit an immune response against tumor cells via the perforin, granzyme B, FAS‐FAS ligand axis, and cytokines and induce apoptosis of tumor cells." (PMID 39631788, 2025). "The granzyme B and perforin double positive CD4 + T cells were increased only in PAK1&4 double KO tumour." (PMID 38797819, 2024). "In MDA-MB-231 and PBMCs xenograft mouse models, 60 mg/kg of Qu significantly inhibits the proliferation of tumor cells compared with the control group (0 mg/kg of Qu) and increases the protein levels of CD8, GZMB, and IFN-γ in tumor tissues." (PMID 39712006, 2024). "The overall tumor assessment with the WTA protocol showed a weak positive correlation between CCR8+ Treg infiltration and GzmB expression in CD8+ T cells." (PMID 38783281, 2024). "In comparison to PD-1+LAG-3- cells, PD-1+LAG-3+ T cells within the tumor exhibited a diminished ability to generate cytokines, including IL-2 and IFN-γ, as well as granules such as perforin (PFN) and granzyme B (GzmB)." (PMID 38390331, 2024). "Activated NK cells secreted key effectors such as Granzyme B, MIP-1α, and IFN-γ to enhance tumor killing function." (PMID 39741300, 2024). "Moreover, the proportions of CD107a+CD8+ T cells, GZMB+CD8+ T cells, and IFN-γ+CD8+ T cells were significantly increased in the anti-TGF-β treatment group compared with the isotype control group, suggesting that TGF-β blockade enhanced the anti-tumor function of CD8+ T cells in the EGFR-mutated TME." (PMID 39004699, 2024). "We found that perforin, granzyme B, IFN-γ, and TNF-α were unevenly distributed within the tumor, showing that these were three pathways to induce activation of N-GSDMD, N-GSDME, and cleaved-CASP3 by perforin, granzyme B, IFN-γ, and TNF-α." (PMID 38740747, 2024). "Although the proportion of tumor-infiltrating lymphocytes remained unchanged, the expression of IFN-γ and granzyme-B in tumor-infiltrating CD8 T cells were significantly higher in CD244fl/flLysMcre mice compared to CD244fl/fl mice." (PMID 38424542, 2024). "An analysis of CD8+ T cells in subcutaneous LCL tumours revealed that the secretion of the anti-tumour cytokines IFN-γ, granzyme-B and perforin was significantly increased in the RIG-I knockout group compared to the control group." (PMID 39322862, 2024). "Ly6G+ and F4/80+ cells isolated from Egfl6+ ascites showed higher inhibition of GZMB and IFN-γ secretion compared with myeloid cells isolated from tumor controls." (PMID 39312740, 2024). "In the adaptive immune response, TGF-β regulates the production of a variety of cytolytic genes including granzyme A, granzyme B, IFNγ, and FAS ligands, which impair the anti-tumor activity of CD8 + T cells, ultimately leading to pro-tumor TME." (PMID 39065562, 2024). "Tumor cells in MEITL are typically CD3+, CD5−, CD7+, CD4−, TIA-1+, granzyme B+, perforin+, and CD103+." (PMID 39447336, 2024). "Cytotoxic CD8+ T cells play a crucial role in tumor immune monitoring and induce anti-tumor immune response by secreting IFN-g and granzyme B (GZB)." (PMID 38762523, 2024). "Tumor-specific T cells highly expressed CD27, IFNG, GZMB and CXCL13 and secreted more effector cytokines for tumor cell killing, as validated experimentally." (PMID 39033098, 2024). "Colocalization data were normalized to tumor area, total amount of CD8+CD3+ T cells for granzyme B staining or CD45+CD68+ cells (macrophages) for CD206 and CD80 stainings." (PMID 38690424, 2024).
tumor (continued). "This enhances the cytotoxic activity of tumor-infiltrating CD8+ T cells and promotes the secretion of GzmB, IFN-γ, and TNF-α." (PMID 39811730, 2024). "MC9999 CAR T cells exhibited cytotoxicity against QNS120 and QNS712 tumor cells, as observed through CD8 T cell degranulation, CD4 T cell degranulation, and granzyme B." (PMID 39498357, 2024). "Coinciding with this data, tumour-infiltrating NK cells in tumours treated with both RMC-4998 and RMC-4550 showed elevated expression of anti-tumour cytotoxic molecule Granzyme B." (PMID 39322643, 2024). "Further, IHC analysis revealed that maraviroc attenuated Treg cell infiltration into the TME, which was accompanied by a marked increase in the expression of the cytotoxic factors Granzyme B and IFN-γ in the tumor area." (PMID 39261943, 2024). "The CD56dimCD16hi subsets of NK cells within the tumor tissue showed lower expression levels of cytotoxic genes like PRF1, GZMB, GZMA, GZMH, and GZMK compared to normal tissues." (PMID 38552055, 2024). "Recently, it has been found that GzmB can directly cleave GSDME in tumor cells, thereby inducing pyroptosis and further activating anti-tumor immune responses." (PMID 38380334, 2024). "In contrast, granzyme B (GZMB) and perforin expression was decreased by C5aR1hi macrophages pre-incubated with olaparib-treated T127 tumor cells." (PMID 38802355, 2024). "OS-high patients, on the other hand, showed increased tumor-cell PD-L1 expression and i-CD8 granzyme-B expression." (PMID 39238637, 2024). "In summary, these data show that tumor cell-extrinsic Axl expression impacts the infiltration of CD8+ and Granzyme B+ cells to liver tumors." (PMID 38673795, 2024). "Subsequent flow cytometry analysis revealed that the combination therapy of STM2457 with anti‐PD‐1 reduced CD8+ T‐cell exhaustion in B16 tumours and significantly enhanced CD8+ T‐cell cytotoxicity by upregulating the expression of IFNγ and GzmB." (PMID 39568154, 2024). "One approach that can show this effect is a tracer targeting granzyme B. Granzyme B is secreted by CD8+ T cells and natural killer cells involved in the T cell-mediated tumor cell death process." (PMID 38182929, 2024). "Consistently, a higher proportion of tumor‐infiltrating T cells exhibited expression of the T cell activation marker CD69 and effector molecules GZMB and IFNγ in the combination treatment group as compared with to the control or single drug treatment group." (PMID 39412086, 2024). "Immunohistochemical staining of the tumor cells was positive for CD3, CD5, CD7, CD8, granzyme B, and TIA." (PMID 38404589, 2024). "In the TME, human CD2high pDCs exhibit elevated levels of granzyme B, TRAIL, and lysozyme, which curtail tumor cell proliferation and mediate contact-dependent killing of tumor cells." (PMID 38512518, 2024). "These tumor-infiltrating CD8+ T cells were functional CTLs, as evidenced by the expression of granzyme B (GZB) and the effector cytokines IFN-γ and TNF-α." (PMID 38349740, 2024). "The groups of CDEVs and CDEVs-PTX showed a rise in the production of GzmB, IFN-γ, and TNF-α, which provides support for the good tumor suppression effect." (PMID 39811730, 2024). "The tumor cells also express cytotoxic molecules, including TIA-1 and granzyme B, whereas CD3 and CD7 are always diminished or lost." (PMID 38792976, 2024). "Immunohistochemistry (IHC) analysis supported these findings, revealing increased CD56, perforin, and granzyme B protein expression, indicating CCN4-induced tumor necrosis and upregulated NK cell infiltration." (PMID 38694508, 2024). "GZMB, which can inhibit aberrant IL‐17 production in CD4+ T cells, thereby impeding angiogenesis and subsequent tumor development, was upregulated in CD4+ Th17 cells in HB group." (PMID 39135526, 2024). "Neutralizing antibodies against IFNγ or granzyme B suppressed CTL cytotoxicity and reduced apoptotic markers in tumor cells." (PMID 39292167, 2024).
tumor (continued). "Additional evidence supporting the tumor-combating capabilities of pDCs is their positioning within the tumor stroma of CRC, in close proximity to cytotoxic CD8+ T cells that produce granzyme B." (PMID 38927922, 2024). "When we compared tumor Teff 1 with normal Teff 1, we observed an increased level of GNLY, GZMB, and IFNG was accompanied by higher HAVCR2 (TIM-3)." (PMID 39454432, 2024). "Tumors formed by CT26 KO2 + Mlh1 induced partial expression of perforin, granzyme B, and TNF-α and partial activation of N-GSDMD and N-GSDME, which also inhibited tumor growth in CT26 KO2 + Mlh1, with little difference in tumor volume compared to CT26 KO." (PMID 38740747, 2024). "Recent studies have shown that GZMB cleaves GSDME-mediated pyroptosis in target cells, leading to enhanced anti-tumor immunity and reduced tumor growth." (PMID 38773976, 2024). "This was companied with a similar reduction of intra-tumor CD8+ T cells and cytotoxicity factor TNFA and GZMB." (PMID 38388466, 2024). "What's more, percentage of PD-1+ cells, the major immune checkpoint, fell down and granzyme B (GZMB) expression in CD8+ T cells was dramatically enhanced, indicating improved anti-tumor effects." (PMID 38164172, 2024). "The analysis revealed that the expression of T-cell effectors, including FasL, GZMB, PRF1, and IFNγ, was remarkably repressed in the tumor microenvironment." (PMID 39201460, 2024). "Vaccine specific T cells in IL-2/CD25 fusion protein treated mice expressed higher levels of Granzyme B as well as IFN-γ, showed a less exhausted phenotype and facilitated an improved anti-tumor immune response." (PMID 39114660, 2024). "Our results showed that the expression of CXCL9, CXCL10, GZMA, GZMB, PRF1 and IFNG was significantly higher in tumor tissues than in adjacent normal tissues in GC patients." (PMID 39376571, 2024). "Only with simultaneous activation of the Vδ2 T cell TCR, which recognizes phosphoantigens on stressed, infected or tumor cells, did CAR-DAP10 signaling mount a full response with release of IFN-γ, TNF-α, IL-2, IL-4, GzmB and cytotoxicity against tumor cells." (PMID 39061247, 2024). "Our findings demonstrated a significant reduction in the expression of CD4, CD8, and granzyme B (GZMB) in Nfkb2‐overexpressing MC38 tumor tissues and CRC tumor samples with high NFKB2 expression." (PMID 38660687, 2024). "CD8+ T cells are crucial in antitumor immunity, effectively eliminating tumor cells via releasing cytotoxic molecules, namely IFN-γ and GZMB." (PMID 38744851, 2024). "We further measured the expression of IFN-γ, GZMB, and PD1 in tumor-specific T cells using flowcytometry." (PMID 39033098, 2024). "Blocking Tr1 cell granzyme B and perforin led to a notable decrease in TAM-specific cell death, allowing the tumor cell lines to thrive in this setting." (PMID 38509593, 2024). "KD of iRhom1 via the NPs led to a significant improvement in tumor immune microenvironment as evident from increases in both the total numbers of CD8+ T cells and the numbers of functional (IFNγ+ or GzmB+) CD8+ T cells." (PMID 38177179, 2024). "Further analysis showed that LC treatment not only increased the proportion of tumor-infiltrating CD8+ T cells but also enhanced the production of interferon (IFN)-γ (effector cytokine) and CD107a (degranulation marker for perforin/granzyme B)." (PMID 38263463, 2024). "The results indicated that IFN-γ, GZMB, and PD1 were significantly upregulated in tumor-specific T cells." (PMID 39033098, 2024). "Adaptive immune mediators included IL‐12, Granzyme B, CD40, PD‐L1, and IL‐17D, suggesting broad effects of alpha 1‐oleate treatment on the tumor tissues." (PMID 38553868, 2024). "The expression of granzyme B produced by CD8+ T cells was detected in the tumor tissues, and the “EcN-cypate + HBO + laser” group presented the highest fluorescence signals." (PMID 38886343, 2024).
tumor (continued). "In both the Axi-cel and Tisa-cel CD8 CAR T cells, >60% of the EM cells expressed both GZMB and GZMA, consistent with the role of TEM cells as memory population with immediate cytolytic capability catalyzing anti-tumor killing." (PMID 38307835, 2024). "In the tumor tissues of the AA and anti-PD1 co-treatment group, the number of granzyme B-positive cells was significantly higher than that in the AA alone or anti-PD1 treatment groups." (PMID 39896806, 2024). "In comparison, SkOV3 killing is significantly decreased when both GZMB and FasL are blocked, implying that CAR T cells employ redundancy in cytotoxic mechanisms to promote killing efficiency of tumor cells." (PMID 38307835, 2024). "This leads to the enhanced secretion of IFN-γ, TNF-α, Granzyme B, and Perforin, which in turn boosts the cytotoxic function of CD8+ T cells, promoting more effective tumor destruction." (PMID 38184630, 2024). "The inhibitory effect of quercetin dihydrate on tumor growth is mediated by the reactivation of T cells, as evidenced by increased protein levels of the CD8, granzyme B (GZMB), and IFN-γ in the tumor tissue." (PMID 39690423, 2024). "With GZMB as a key proponent in tumor cell apoptosis, focus has shifted to the role of the GZMB inhibitor, protease inhibitor-9 (PI9), in tumor resistance." (PMID 38307835, 2024). "The loss of Sb9 in Tregs, TAMs, and MDSCs drive them more sensitive to GzmB-mediated killing within the TME, ultimately leading to less infiltration of these immunosuppressive cells into the tumor." (PMID 38966643, 2024). "After expansion, potential effector functions of γδ T cells were demonstrated by IFN-γ, TNF-α and granzyme B production upon PMA/ionomycin stimulation and effective killing capacity of multiple tumor cell lines was confirmed in killing assays." (PMID 38426099, 2024). "Areas annotated as having diffuse immune infiltration showed higher levels of MHCI (beta-2-microglobulin, B2M) and checkpoints IDO1, PD-L1, PD-1 and Tim-3 in tumor AOIs, and higher levels of T-cells (CD3) and Granzyme B in immune AOIs." (PMID 39026018, 2024). "At the same time, we found that the number of perforin, granzyme B, IFN-γ, and TNF-α released from between CT26 (Ctrl) and CT26 KO tumor tissue was significant." (PMID 38740747, 2024). "The proliferation, apoptosis or ability to secrete effector cytokines (e.g. Granzyme B and IFN-γ) of T cells are related to their killing effect on tumor cells." (PMID 38231305, 2024). "An improved tumor inhibition, an increased TIL infiltration and expression of granzyme B, perforin, as well as CD69 were found in mice treated with PHD2/3 KO CD8 T cells, when analyzed 7 days after ACT." (PMID 39242595, 2024). "Consistently, OT-I T cells co-cultured with thimerosal-treated tumor cells also upregulated the expression levels of activation markers CD25, CD69, and effector molecules such as intracellular Granzyme B (GZMB) and IFNγ." (PMID 39349845, 2024). "Our results demonstrated the reversal of Granzyme B and IFNγ inhibition by CD8 + T cells from tumor tissues following TIGIT blockade." (PMID 38216949, 2024). "It is conceivable that macrophages in TIME have the same property of secreting GzmB, and the occurrence of emperitosis greatly inhibits TIME viability, which in turn accomplishes tumour immune escape." (PMID 38652105, 2024). "GzmB expression by tumour-specific CD8+ T-cells in tumours and lungs were similarly enhanced when mice were infected at day 4 or 10 post tumour cell transplantation." (PMID 38271469, 2024). "Granzyme B, released by activated effector CD8+ T lymphocytes, participates in the direct tumor-killing mechanism." (PMID 39072335, 2024). "Our findings revealed that the inhibition of Granzyme B and IFNγ by CD8 + T cells from tumor tissues was reversed upon CD155 knockdown." (PMID 38216949, 2024).